PMS2 (PMS1 homolog 2, mismatch repair system component)
Diseases named in the same sentence as PMS2 in open-access papers (continued):
Sharing a sentence is not in itself a finding about the gene and the disease.
cancer (continued). "If MLH1/PMS2 loss serves as a predictive marker for sensitivity to HER inhibitors across cancer types, the already routine identification of these markers in these other cancer types can be married to a clinically feasible targeted therapy." (PMID 34011995, 2021). "Current testing criteria fail to identify individuals with P/LP variants in PMS2 and other actionable cancer genes." (PMID 34585040, 2021). "The clinical impact of pathogenic PMS2 variants are currently debated, but it is widely accepted that PMS2 variants confer a much lower cancer risk than the other MMR genes." (PMID 33193653, 2020). "Loss of MLH1 and PMS2 expression was observed in the cancer cells of both biopsy specimens and resected lymph nodes." (PMID 32394212, 2020). "Carrying PMS2 germline mutation (c.1577delA) confers an extremely high susceptibility of suffering from LS-associated cancers." (PMID 31860975, 2019). "Mutations of MLH1 and PMS2 contribute to microsatellite instability and increased mutation rates in cancer cells." (PMID 30370249, 2018). "This patient had a family history of cancer, however, only somatic mutations were detected in PMS2; p.Q288* (pathogenic mutation) and p.H701R (variant, likely pathogenic)." (PMID 29755653, 2018). "Executing the proposed workflow resolves cancer risk associated with the last five exons of PMS2 for the majority of samples with short-read NGS alone." (PMID 30268105, 2018). "This is the first report of the founder PMS2 mutation - NM_000535.5:c.1500del (p.Val501TrpfsTer94) in exon 11 and its associated cancers in this family." (PMID 28381238, 2017). "In 2015 the Leiden group, in collaboration with the Dutch registry, described cancer risks in a large series of PMS2 mutation carriers." (PMID 26973060, 2016). "Information in the literature on cancer risk for carriers of a PMS2 mutation is limited and only estimates of relative risk (RR) are available." (PMID 26973060, 2016). "The exact cancer risks conferred by PMS2 mutations are unclear, but they are thought to be lower than other MMR gene mutations." (PMID 26484312, 2015). "Among the various MMR genes, the PMS2 gene has been relatively understudied in relation to cancer risk." (PMID 26036629, 2015). "It has been demonstrated that PMS2-mutation carriers develop cancers that show selective loss of PMS2 by IHC and that this is advocated to be followed by PMS2 mutation testing in blood." (PMID 24790682, 2014). "Mutations in PMS2 are important in the progression of human cancer, and deficiency of human PMS2 is associated with impaired immunoglobulin class switch recombination." (PMID 23326468, 2013).
cancer (continued). "Overall, substantial deficiencies in protein expression of DNA repair proteins Pms2, Ercc1 and Xpf frequently occur in a coordinated manner in extensive regions, involving as many as 1 million crypts, near cancers, and also occur within cancers." (PMID 22494821, 2012). "Communicating cancer risk to PMS2 mutation carriers and deciding which surveillance protocol is adequate for the families is a difficult task for the genetic counsellor/geneticist." (PMID 20487569, 2010). "This discovery led the researchers to make the interpretation that biallelic inactivation of the PMS2 gene would be needed in order to produce predisposition towards cancer, thereby confirming the idea of the two-hit model proposed by Knudson." (PMID 19466295, 2009). "A deficiency in the post-meiotic segregation increased 2 (PMS2) gene correlates strongly with impaired immunoglobulin class switch recombination; moreover, mutations in this gene are significantly associated with human cancer progression." (PMID 40142220, 2025). "However, PMS2-related syndromes primarily confer cancer predisposition in childhood or adulthood, without established causality to specific congenital cardiac or vascular anomalies." (PMID 41555925, 2025). "However, pathogenic PMS2 variants are associated with the lowest cancer risks among LS-related MMR gene mutations." (PMID 40452892, 2025). "The PMS2 missense variant identified in the index cases of the present study (NM_000535.7: c.184G>A; p.Gly62Arg) has never been described in the literature in patients with a personal and/or family history of cancer." (PMID 40723192, 2025). "The DNA MMR gene PMS2 has been defined as a low-penetrance gene for cancers associated with LS." (PMID 40723192, 2025). "In this report, we share the impact of the diagnosis and challenges during the clinical management of two brothers with CMMRD from a non-consanguineous family harboring compound heterozygous variants in the PMS2 gene, who presented with different phenotypic manifestations and cancer spectrum." (PMID 38773265, 2024). "In addition, we wanted to describe the frequency, spectrum and penetrance of cancers in our cohort of carriers of pathogenic and likely pathogenic PMS2 variants." (PMID 39334433, 2024). "Additionally, people with variants in low-penetrance genes, such as MSH6 and PMS2, have a lower risk of developing a cancer associated with LS, leading to families with unaffected generations and showing fewer clear patterns." (PMID 37864171, 2023). "We suggest that MAT1A and WRN variants and PMS2 loss could contribute to the hereditary cancer predisposition phenotype observed in this family." (PMID 37628631, 2023). "Cancer is also common in elderly women with PMS2 mutations (13%)." (PMID 36091691, 2022). "A review of several studies investigating colorectal cancer (CRC) suggested that a hypomorphic PMS2 variant may cause early onset of cancer." (PMID 33247565, 2021). "For those with the PMS2 pathogenic variant, endometrial cancer may develop later, and the cancer risk is often lower than that of individuals with the other three pathogenic variants, with a cumulative incidence of 0 before age 50 and 9.3%-12.8% at age 60–70." (PMID 34118983, 2021). "As a result, the loss of MLH1 and PMS2 expression was observed in both primary cancer and the metastatic lymph node, suggesting that the abnormality of MLH1 could be affected." (PMID 32394212, 2020).
cancer (continued). "As such, mutations in PMS2 are directly associated with an increased risk of cancer." (PMID 30723478, 2018). "Furthermore, MLH1 germline mutation was identified in 23% of cancers with isolated immunohistochemical PMS2 loss." (PMID 28510097, 2017). "In 16 cancers Pms2 was deficient when Mlh1 protein expression was present." (PMID 22494821, 2012). "Although primary mutations of PMS2 are uncommon, the inclusion of PMS2 immunohistochemistry may aid the identification of MLH1 germline mutations in MSI-H cancers that continue to express MLH1." (PMID 16106253, 2005). "Furthermore, a DES in PMS2, a gene for a component of mismatch repair, that resulted in a I18V change, has been experimentally linked to the induction of microsatellite instability, a hallmark of mismatch repair-deficient cancer." (PMID 38672084, 2024). "In cases of MLH1/PMS2 protein losses in tested cancers, beside the loss-of-function mutation of MLH1, promoter methylation may also be the genetic cause; therefore, a methylation analysis can be performed with in-house PCR protocols or using commercial kits such as SALSA MS-MLPA." (PMID 38655493, 2024). "Similarly, the observed risk of dying from ovarian cancer in path_MSH6 or path_PMS2 carriers diagnosed before 50 years of age was 0%, and in these carriers, prophylactic oophorectomy before 50 years of age solely for cancer prevention reasons is considered unwarranted and unethical." (PMID 37821984, 2023). "Interestingly, a report on CMMR-D patients carrying a biallelic NM_000535.5:c.2002A>G (p.Ile668Val) variant described an attenuated phenotype where the age at first cancer was strikingly different, namely 22 years for carriers of this variant versus 8 years for truncating PMS2 variants." (PMID 36895471, 2023). "Heterozygous PMS2 mutation carriers may have a 25–32 % lifetime risk of any cancer." (PMID 26873718, 2016). "Because monomeric PMS2 is highly unstable, and the reported mutation rate of PMS2 is quite low in various cancers, we hypothesized that certain types of exogenous DNA-damaging agents may rapidly degrade PMS2 production and disrupt the MMR system for facilitating carcinogenesis." (PMID 20178594, 2010). "However, PMS2 mutations are quite rare in HNPCC as well as various other cancers." (PMID 20178594, 2010). "Combined loss of MSH6 and PMS2 (MSI-H) was found in 30% of cases, particularly in poorly differentiated tumors, T3 stage tumors, stage II and III cancers, and node-positive groups." (PMID 41907888, 2025).
cancer (continued). "Three LS cases were missed with MMR IHC (1 MSH6 and 2 PMS2 carriers), it is possible these patients had sporadic cancers unrelated to their LS carrier status." (PMID 39886913, 2025). "Clinical genetic repositories analysis showed DNA repair genes, such as MLH1, PMS2 and MSH3, are associated with cancer phenotypes, suggesting potential limitations as drug targets." (PMID 39801710, 2025). "Mismatch repair genes MLH1, PMS2 and MSH3 displayed an increased number of pathogenic alleles and were linked to cancer phenotypes, suggesting potential limitations as drug targets." (PMID 39801710, 2025). "Another finding was the ubiquitous loss of MLH1 protein in conjunction with PMS2 absence, implying dMMR and suggesting a potential use as surrogate biomarker for rhesus CRC diagnostics due to its clear-cut separation of cancer cell clusters and healthy tissue." (PMID 38504345, 2024). "In the non‐cancer cohort, 25/492 (5%) participants carried 17 unique P/LP variants in ATM, BRCA2, BRIP1, CHEK2, MUTYH, NBN, and PMS2 genes." (PMID 38308423, 2024). "Our gain-of-function studies reveal that PMS2 overexpression increases the migration and invasion capabilities of cancer cells, crucial for the initiation of metastasis." (PMID 38714954, 2024).
cancer (continued). "This distinct pattern of MLH1/PMS2 double loss matches the IHC pattern associated with MLH1 abrogation in human CRCs and allows a distinctive delineation of cancer cell clusters and adjacent healthy cells." (PMID 38504345, 2024). "PMS2 (OMIM * 600259) is nevertheless the least described of the four MMR genes, both in terms of mutation spectra and penetrance of cancer." (PMID 39334433, 2024). "Both cancers were hypermutated with mutational signatures of MMR deficiency, loss of PMS2 expression on immunohistochemistry (IHC) and high exomic MSI burden (colon: 207; PDHGG: 1360; median for MMR-proficient controls: 17)." (PMID 38773265, 2024). "Immunohistochemical (IHC) staining of the MMR protein PMS2 (as well as MLH1) exhibited nuclear expression in the carcinoma nuclei." (PMID 38243056, 2024). "All patients affected by d-MLH1 cancers were tested for the MLH1 and PMS2 genes in germinal setting, and pathogenic variants (class 4 and 5) of the MLH1 gene were observed in 23 patients." (PMID 38003003, 2023). "All seven cancers showing concomitant MLH1 somatic hypermethylation and germline MLH1 variants displayed immunohistochemical loss of expression of both MLH1 and PMS2, presented with a high level of MSI, and belonged to five families." (PMID 38003003, 2023). "A less aggressive form of surveillance is recommended for MSH6 and PMS2 carriers, with the first colonoscopy executed at 35 and 40 years of age, respectively, unless there is a family history of earlier cancers." (PMID 37568596, 2023). "At the same time, in a large-scale study of BC women aged 35–59 years, who were mainly of Northern and Western European descent, PVs in CHEK2, ATM, PALB2, and PMS2 genes were the most frequent among the 25 cancer genes tested, after PVs in BRCA1/2." (PMID 37791908, 2023).